VHL (von Hippel-Lindau tumor suppressor)
Diseases named in the same sentence as VHL in open-access papers (continued):
Sharing a sentence is not in itself a finding about the gene and the disease.
pancreatic cancer (26 papers, 2014 to 2025). "Concurrently, the SUMO ligase PIAS4 mediates SUMOylation of the VHL, inducing VHL oligomerisation and loss of its normal function, which promotes pancreatic cancer growth." (PMID 41463025, 2025). "Patients with missense mutations (type 2 VHL) exhibit a higher prevalence of pancreatic tumors and a hotspot on codons 161/67 in exon 3 is associated with higher risk of metastases compared to truncating mutations or large deletions (type 1 VHL)." (PMID 36699028, 2022). "However, PNETs comprise only 5% of pancreatic cancers and the association between PNETs and VHL is less than 0.5%." (PMID 34963877, 2022). "KLHL7-based biodegraders only degraded the anchored POI in Jurkat cells, a T cell line, while VHL depleted less efficiently the same anchored POI in pancreatic cancer cells." (PMID 38746666, 2024). "This indicates UBE2S takes part in promoting endodermal metastasis and metastasis in pancreatic cancer cells in vitro and in vivo by inhibiting promoter activity in the VHL/HIF-1α/STAT3 pathway." (PMID 38312603, 2024). "Many of them have been tested in clinical studies, and some have been approved recently for clinical use for localized pancreatic tumors in patients with VHL." (PMID 36980625, 2023). "To assist in managing patients with VHL and metastatic pancreatic tumors, we suggest an algorithm for choosing the optimal medical intervention for patients in this rare scenario." (PMID 36980625, 2023). "Approximately a fifth of patients with VHL develop tumors in the pancreas, and most of these tumors are localized and can be followed or resected in surgery." (PMID 36980625, 2023). "Several studies demonstrated that miR-21 directly decreased the expression of VHL in glioblastomas, papillary thyroid carcinoma, and pancreatic cancer." (PMID 36522730, 2022). "However, the low level of expression of VHL-sdAb ALFA might explain why it was less efficacious in pancreatic cancer cells, with 25% of GFP signal drop in MIA PaCa-2 and PDAC087T, compared to above 50% in the other cell lines." (PMID 38746666, 2024). "Furthermore, PIAS4 could promote the activity of hypoxia signaling pathway by interacting with VHL, which leads to VHL SUMOylation and impairing VHL's function in pancreatic cancer cells." (PMID 33273928, 2020). "Found a 7 gene panel (MDR1, SRBC, VHL, MUC2, RB1, SYK, and GPC3) that detects colorectal and pancreatic cancers with 63.16% sensitivity, 84% specificity, and AUC of 0.8177." (PMID 36980276, 2023). "The study revealed that in pancreatic cancer cells, the expression of the UBE2S gene facilitated the process of epithelial-mesenchymal transition (EMT) by means of the ubiquitin proteasome system and the interaction between UBE2S and VHL." (PMID 38312603, 2024). "More significantly, 5–10% of VHL patients develop pancreatic tumors, which are most commonly non-secretory islet cell tumors known as pancreatic neuro-endocrine tumors (pNET)." (PMID 36699028, 2022). "Since the gene panel did not include GNAS, VHL, or RNF43, we could not rule out the possibility of IPMN-derived pancreatic cancer associated with these genes." (PMID 36980386, 2023). "However, given the lack of additional VHL patients with pancreatic carcinoma and the persistence of heterozygosity in adenocarcinoma, it is unlikely that VHL gene alterations contribute to the development of pancreatic adenocarcinoma in VHL patients." (PMID 37251595, 2023). "To demonstrate that the observed cell proliferation inhibition of three pancreatic cancer cells is due to CREPT degradation rather than the disruption of the CREPT homodimers caused by the non-degrading peptide, we synthesized a PRTC mutant lacking the VHL recruiting domain, named PRTC-v." (PMID 32206117, 2020).
Pancreatic cysts (25 papers, 2012 to 2026). A cyst of the pancreas that possess a lining of mucous epithelium. "We report a case where next-generation sequencing (NGS) of pancreatic cyst fluid resulted in the first diagnostic clue to VHL." (PMID 41710795, 2026). "Since the association between the pancreatic cysts and DM in patients with VHL observed in this study is in contrast with the results presented in previous studies, this association should be considered with caution." (PMID 38529425, 2024). "This study examined the association between the area occupied by the pancreatic cysts and DM in 36 patients with VHL." (PMID 38529425, 2024). "In agreement with this notion, pancreas-specific Vhlh (the murine homolog of VHL) inactivation in mice results in the formation pancreatic cysts, loss of exocrine pancreas and fat replacement." (PMID 30209343, 2018). "Since somatic LOH of wild-type VHL allele has been verified in pancreatic cysts in VHL, we reviewed the existing literature based on RCC cell line studies to gain insight into the effect of pVHL on pancreatic cell regulation and cyst development." (PMID 23384121, 2013). "In contrast, exome sequencing of sporadic human pancreatic serous cysts only found chromosome 3p loss/VHL mutations as recurrent genetic lesions, suggesting that VHL loss is sufficient for pancreatic cyst development." (PMID 23384121, 2013). "Thus, further studies with larger sample sizes and more detailed information regarding glucose metabolism are necessary to evaluate the association between pancreatic cysts and DM in patients with VHL." (PMID 38529425, 2024). "Various tumors, such as HB in the CNS, RA, Pheo, RCC, neuroendocrine tumors in the pancreas, renal, and pancreatic cysts, have been found to develop through the same process as that in the inactivation of the VHL gene and subsequent functional loss of the pVHL-elong in B-C (VBC) complex." (PMID 23843833, 2012). "A few studies have reported that multiple pancreatic cysts may cause DM in patients with VHL." (PMID 38529425, 2024). "If such an association is identified, routine screening for DM in patients with VHL who have many pancreatic cysts can lead to an early diagnosis of DM." (PMID 38529425, 2024). "Future studies should focus more on VHL and also other E3 ubiquitin ligase genes, which appear to be involved in pancreatic cysts." (PMID 23384121, 2013). "Here, we give a comprehensive overview of various pVHL functions, focusing on those that can potentially explain pancreatic cyst development in VHL disease." (PMID 23384121, 2013). "Monogenetic diseases like VHL provide insights which can be translated to pancreatic cysts in general." (PMID 23384121, 2013). "Remarkably, pancreatic cysts occur in approximately 70% of VHL patients, making it the only hereditary tumor syndrome with such a discernible expression of pancreatic cysts." (PMID 23384121, 2013). "In 12% of patients, pancreatic cysts are diagnosed as the only sign of VHL." (PMID 38779573, 2024). "Between 35 and 70% of patients with VHL have pancreatic cysts." (PMID 34963877, 2022). "Approximately 35–70% of the patients with VHL have pancreatic cysts." (PMID 34963877, 2022). "Approximately 35–70% of patients with VHL have pancreatic cysts." (PMID 34963877, 2022). "pNETs are present in 10 to 17% of VHL patients and pancreatic cysts occur in about 70%." (PMID 23384121, 2013). "In both pNETs and pancreatic cysts, LOH of VHL wild-type allele was confirmed." (PMID 23384121, 2013). "Thus, it was speculated that the presence of pancreatic cysts may affect the endocrine function of the pancreas and that patients with VHL who have a large area occupied by pancreatic cysts are more likely to have DM than patients without pancreatic cysts." (PMID 38529425, 2024). "Therefore, it is likely that pancreatic cysts in VHL are a result of similar consequences." (PMID 23384121, 2013).
Pancreatic cysts (continued). "CNS HB wasthe most common VHL-related tumor (67.92%), followed by adrenal PGL (64.15%),pancreatic cysts (47.17%), and PNET (41.51%)." (PMID 39945572, 2025). "The findings of the present study suggest that patients with VHL who have a large area occupied by pancreatic cysts are more likely to have DM than those without." (PMID 38529425, 2024).
hepatocellular carcinoma (24 papers, 2014 to 2026). A malignant tumor that arises from hepatocytes. "Unlike the VHL diseases and ccRCC, emerging studies reported that mutations in VHL are rare in lung cancer and hepatocellular carcinoma." (PMID 36813923, 2023). "Prior studies demonstrated that cancer cells release glutamate, but our data demonstrate that increased glutamate efflux occurs in hepatocellular carcinoma cells in response to hypoxic conditions and in ccRCC cells due to VHL loss-of-function." (PMID 25326682, 2014). "Interestingly, high levels of these exosomes were found in hepatocellular carcinoma patients, and a low survival rate was associated with low VHL presence and high HIF-1α." (PMID 39697630, 2024). "Unlike sporadic clear‐cell renal carcinomas, VHL mutation is rarely observed in hepatocellular carcinoma (HCC) and the regulatory mechanisms of pVHL‐HIF signaling remain elusive." (PMID 32328410, 2020). "This study confirms that HaloPROTAC3 can induce the degradation of HT fusion proteins in the human hepatoma Huh7 cell line and human primary hepatocytes, demonstrating that the host E3 ligase VHL can be harnessed for targeting the liver stages of human Plasmodium species." (PMID 40419780, 2025). "For instance, adipocyte-derived exosomes containing miR-32a and miR-32b could activate the von Hippel-Lindau-HIF-1α (VHL-HIF-1α) pathway in hepatocellular cancer cells, leading to increased resistance to 5-FluoroUracile." (PMID 39697630, 2024). "For instance, recent studies have identified miRNA binding site polymorphisms in genes implicated in migration, invasion, and angiogenesis, such as RASA1, COL1A2, CA9, CD147, VHL, and RYR3, which can influence susceptibility to hepatocellular carcinoma (HCC)." (PMID 41409896, 2025). "Additionally, they further demonstrated, in vitro, that such exosomes when delivered to hepatocellular carcinoma (HCC) cells, induce their proliferation, migration, and chemoresistance through the von-Hippel-Lindau (VHL)/HIF-1α axis." (PMID 34283044, 2021).
cyst (22 papers, 2010 to 2026). A sac-like closed membranous structure that may be empty or contain fluid or amorphous material. "Tumor or cyst development in VHL disease is linked to somatic inactivation or the loss of the remaining wild-type VHL allele." (PMID 37445575, 2023). "Combined loss of VHL and GSK3β disrupts ciliary maintenance, and it is considered a key player in the cyst-dependent CCRCC progression pathway." (PMID 37444462, 2023). "Overexpression of EGFR was present in a variety of VHL mutations, and the volume of the cyst was related to the upregulation of EGFR (r = 0.532; p = 0.023)." (PMID 32432044, 2020). "Additional genes provided a marginal improvement in sensitivity but were associated with cyst type (e.g. VHL) and grade (e.g. SMAD4)." (PMID 31258847, 2019). "Sex and age of patients, as well as type of von Hippel-Lindau (VHL) mutation, associated cyst and solid tumor size are stated." (PMID 30214643, 2018). "Interestingly, just as VHL is an early cancer-initiator gene that requires further downstream molecular events, cyst formation cannot rely on VHL deficiency alone." (PMID 37444462, 2023). "For small cysts that cannot be excised, unroofing and fulguration of the cyst base are advised, as the cyst walls in VHL patients, lined with clear cells, have the potential to become malignant within 3–7 years." (PMID 39201746, 2024). "In this review, we conduct a complete overview of pVHL functions to explain cellular events involved in cyst development in the context of VHL." (PMID 23384121, 2013). "Epithelial cells lining simple cystic lesions display a reduced frequency of primary cilia, similar to cysts in human VHL patients, further supporting the involvement of pVHL in maintenance of primary cilia and suppression of cyst formation." (PMID 23606570, 2013). "Endoscopic ultrasound with fine-needle aspiration was performed and standard cyst fluid analysis was nondiagnostic, but cyst fluid NGS identified a pathogenic VHL mutation." (PMID 41710795, 2026). "To study VHL's role in ccRCC formation, we previously developed a novel conditional knockout mouse model that mimicked the features of kidney inflammation and fibrosis that lead to cyst formation and hyperplasia." (PMID 34257811, 2021). "One study used data from 850 patients, incorporating clinical variables (age, gender, race, and symptoms), cyst characteristics (size and number), and cystic fluid molecular markers (CFMM) including vascular endothelial growth factor (VEGF), CEA, and Von Hippel–Lindau (VHL) mutations." (PMID 40805252, 2025). "As a result, we speculate that due to the overlying of other abnormal genes, some cyst‐lining cells of MCRN-LMP on the basis of VHL gene abnormality, further proliferate to form solid expansive nodules, and then develop into ccRCC with cystic component similar to MCRN-LMP." (PMID 36810118, 2023). "PTEN loss per se is not sufficient to induce cyst development; conversely, the concomitant loss of PTEN and other tumor suppressor genes, such as Von Hippel-Lindau (VHL) and TSC, was implicated in cyst formation." (PMID 28353628, 2017). "The test integrated three data elements: presence of VHL mutation but absence of GNAS mutation, decreased expression of a VEGF-A protein, and a combination of factors (solid component of cyst seen on imaging, aneuploidy, and presence of mutations in certain genes)." (PMID 37887627, 2023). "Double-knockout mouse models for both VHL/HIF-1α and VHL/HIF-2α however do not develop kidney cysts, indicating the importance of both proteins for cyst formation." (PMID 28934953, 2017).
retinal hemangioblastoma (22 papers, 2015 to 2025). A hemangioblastoma that arises from the retina. "The study found that patients with mutations in the α domain of the VHL gene had a higher prevalence of retinal hemangioblastomas compared to individuals with missense mutations in the functional β domain." (PMID 35205407, 2022). "von Hippel-Lindau (VHL) disease is caused by a mutation of the VHL gene and characterized by the development of retinal hemangioblastomas (RH)." (PMID 35960779, 2022). "It is also similar to the pathological structures of von Hippel–Lindau (VHL) gene mutation-related retinal capillary hemangioblastoma (RCH), which mainly have proliferating-endothelial cells and VHL-deficient foamy (lipid-filled) stromal cells." (PMID 34512255, 2021). "A novel W117R was detected in the VHL gene that caused retinal hemangioblastomas in affected members of a Chinese family." (PMID 30477447, 2018). "Furthermore, the individuals with truncated protein forms who developed retinal hemangioblastoma had lower visual morbidity than patients with other types of VHL mutations." (PMID 35205407, 2022). "They observed that the individuals with truncated VHL proteins may have a decreased risk of developing multiple retinal hemangioblastomas in comparison with individuals who have missense mutations in the VHL gene." (PMID 35205407, 2022). "Therefore, CLU could serve as a potential marker for pVHL function and reflection of VHL gene integrity in VHL-associated retinal hemangioblastoma and hemangioma." (PMID 37685987, 2023). "On the other hand, some studies show that patients develop retinal hemangioblastoma with complete deletion of the VHL gene less frequently than those with a single amino acid substitution in the VHL gene." (PMID 39272694, 2024). "Herein, we present a case diagnosed with VHL based on retinal hemangioblastomas after presenting to our clinic with reduced vision, and the treatment and follow-up of the patient and his relatives." (PMID 28630796, 2017). "In fact, except for retinal hemangioblastomas, the majority of VHL component tumors are sporadic." (PMID 40647474, 2025). "Retinal hemangioblastoma (RH), one of the earliest and most frequent manifestations of VHL disease, originates in the neurosensory retina or optic disc area, and is composed of VHL-inactivated foamy stromal cells and abundant reactive vessels." (PMID 35960779, 2022). "One set of criteria, based on Melmon and Rosen’s review, require either a positive family history of the disease plus a single vHL-associated tumor or the presence of two vHL-associated tumors (one of which must be a CNS or retinal hemangioblastoma) in the absence of a confirmed family history." (PMID 39678829, 2024). "As an ophthalmologist, identifying retinal hemangioblastomas and determining whether they are related to VHL is extremely important for the early diagnosis and treatment of life-threatening tumors and complications that may develop in these patients and their families." (PMID 28630796, 2017).